RAB27A (RAB27A, member RAS oncogene family)
Diseases named in the same sentence as RAB27A in open-access papers (continued):
Sharing a sentence is not in itself a finding about the gene and the disease.
tumor (continued). "Rab27A is reported to have functions outside of exosome release, namely in MMP9 secretion; thus, it remains difficult to discern exosome-dependent from exosome-independent effects on tumor progression." (PMID 30925917, 2019). "Thus, we conclude that inhibition of self-derived exosome secretion by Rab27a blockade promotes intrahepatic and lung metastasis of MHCC97H tumours." (PMID 29725020, 2018). "To test the hypothesis that tumor released exosomes induce tumor innervation, we utilized CRISPR/Cas9 to genetically modify Rab27A and Rab27B in mEERL parental cells." (PMID 30327461, 2018). "Here in this article, in order to illustrate the relationship between Rab27a and NSCLC, we silenced Rab27a gene of NSCLC cells, further explored the changes in cell invasion, migration, proliferation and apoptosis in vitro and tumor model of human NSCLC cells in nude mice." (PMID 29212243, 2017). "Tumor growth curves demonstrated that the H1650-scr and SPC-A-1-scr cells of tumor volume after silenced for Rab27a expression was much lower than corresponding control and normal control." (PMID 29212243, 2017). "In tumor-bearing state, the capability of neutrophils to degranulate is attenuated due to the inhibitory effect of G-CSF/IL-6 on activation of PI3K and p38 MAPK pathways and the expression of Rab27a." (PMID 25587026, 2014). "The absence of Rab27a did not affect tumor proliferation in vitro or in vivo." (PMID 39810420, 2025). "Unlike previous studies focusing on the regulation of tumor sEV secretion led by RAB27A, we found that RAB27A could directly participate in the post-transcriptional regulation of specific proteins within tumor cells." (PMID 37685910, 2023). "Notably, Rab27a upregulates response to inflammatory stimulation by enhancing exocytosis of TNF-α, whereas downregulation of Rab27a correlates with lower neutrophil-mediated tumor cytotoxicity in TME (exocytosis)." (PMID 35927755, 2022). "Since Rab27a and TRAF3IP2 contribute to exosome release and inflammation, respectively, we hypothesized that targeting Rab27a or TRAF3IP2 will reduce inflammation, tumor formation, growth and metastasis of BC in a preclinical breast xenograft model." (PMID 32483202, 2020). "Small hairpin interfering RNA (ShRNA) silencing of the GTPases Rab27a/b and using an inhibitor of sphingomyelinase (GW4869) or annexin/diannexin represent potential strategies to prevent the promoting effects of exosomes on tumor progression, angiogenesis, and metastasis." (PMID 35582044, 2020). "When neutrophils were recruited to peritoneal cavity with CXCL1-expressing cells (C-PC, non-inflammatory), the neutrophils from tumor-bearing mice and pG/pI6-mice showed a protumor phenotype, characterized by higher expression of Bv8 and Mmp9 as well as lower expression of Rab27a and Trail." (PMID 25587026, 2014). "Notably, exosomes derived from Rab27a‐overexpressing lung cancer cells not only promote upregulation of MHC class II, CD80, and CD86 on DCs, but also facilitate CD4+ T cell proliferation and type I cytokine secretion, culminating in effective tumor growth inhibition in vivo." (PMID 41256221, 2025). "Interestingly, when mice were injected with mutant cancer cells that did not have Rab27a, nSMase2, or PD-L1, not only did the local tumor tissue fail to grow, but it also prevented the growth of wild-type tumor cells that were injected at the same time or 92 days later." (PMID 38562933, 2024). "At the level of gene expression, Rab27a GTPase is overexpressed in advanced tumors during the establishment of pre-metastatic niche and is used to regulate vesicle transport, which is related to the non-cellular autonomous control of tumor growth and metastasis." (PMID 35965504, 2022). "Thus, emerging data suggests, that Rab27a could in fact have both cell-autonomous as well as non-cell-autonomous effects on tumor progression, however, this has not been yet studied in a fully immune-competent system in order to address both aspects." (PMID 32355248, 2020).
tumor (continued). "Electron microscopic analysis indicated that silencing Rab27a results in the formation of a porous cell surface in MDAKDRab27a cells, while silencing TRAF3IP2 resulted in a rough surface, suggesting that Rab27a and TRAF3IP2 might be involved in remodeling or destabilization of tumor cell membrane." (PMID 32483202, 2020). "Our study shows that RAB27A, RAB27B, RAB2B, and RAB3B mRNA levels were lower in tumor tissues compared to tumor adjacent, non-malignant tissues (p < 0.001, p = 0.009, p = 0.011, and p < 0.001, respectively)." (PMID 36980570, 2023). "Similar to the results from the MC38 Rab27a−/− tumor-bearing mice, αPD-L1 notably inhibited MC38 Coro1a−/− but not MC38 tumor growth at the same dose." (PMID 36220994, 2022). "At the same time, we found that Rab27A-T23N, which is a dominant negative mutant defective in GTP binding, prohibited tumor formation significantly." (PMID 27556511, 2016). "Interestingly, RAB27A, RAB27B, RAB2B, RAB3B mRNA levels were lower in tumor tissues compared to tumor adjacent, non-malignant tissues (p < 0.001, p = 0.009, p = 0.011 and p < 0.001, respectively)." (PMID 36980570, 2023). "However, in contrast to Rab27a or nSMase2 deletion, ALIX knockdown promotes, but does not suppress the tumor growth." (PMID 33178688, 2020).
cancer (97 papers, 2013 to 2025). A tumor composed of atypical neoplastic, often pleomorphic cells that invade other tissues. "The small GTPase Rab27a has been implicated in several cancer progression mechanisms such as metastasis, cell invasion, or migration." (PMID 39008536, 2024). "Altered expression of RAB27A/B is observed in various human cancers and has been linked to cancer progression in NSCLC, although the mechanism by which RAB27B affects NSCLC is not known." (PMID 37077938, 2023). "A recent meta-analysis found that elevated expression of Rab27a and/or Rab27b is associated with poor prognosis and cancer metastasis." (PMID 34483204, 2021). "Overexpression of Rab27a has been linked to poor prognosis in cancer, presumably in the context of the contribution to the extensive remodeling by systemic EV release." (PMID 32355248, 2020). "Consistently, IFN-γ secretion induced by Lon-mtDNA was increased after Rab27a-shRNA treatment, suggesting that mtDNA accumulation in cancer cells caused by Rab27a-shRNA induces STING-dependent IFN expression and secretion." (PMID 33268351, 2020). "The majority of clinicopathological evidence has indicated that elevated Rab27A/B expression is associated with shorter survival times, more advance cancer stages, and distant metastasis of cancer." (PMID 30081925, 2018). "In this study, we also linked Rab27A with NF-κB signaling, which is closed related to cancer cell proliferation and chemoresistance." (PMID 29088864, 2017). "For these experiments we used cancer cells that had been rendered deficient in exosome secretion by knockdown of Rab27a as described." (PMID 25596732, 2015). "Both in vivo and in vitro studies have demonstrated the role of Rab27a in promoting proliferation and invasion and suppressing apoptosis, processes that are associated with cancer metastasis and progression." (PMID 24587032, 2014). "Thus, the inhibition of Cdn5 leads to a similar (albeit potentially less cancer-specific) consequences as the loss of Rab27a/b." (PMID 40408475, 2025). "It has been proved that the overexpression of Rab27a is related to the poor prognosis of cancer and may be related to the extensive remodeling caused by the release of systemic EVs, which contributes to the biogenesis of EVs." (PMID 37902101, 2023). "Consequently, Rab27A and exosome secretion are intrinsically linked to cancer cell invasion." (PMID 30925917, 2019). "Based on this, Rab27A suppression can potentially become a therapeutic target for EV-related cancer." (PMID 40722712, 2025). "Blocking miRNAs by knocking down Rab27a or inhibiting the release of EXOs in cancer tissue by Dicer enzyme knockout attenuated this additional injury effect." (PMID 40360476, 2025). "Rab27A and Rab27B inhibition have been shown to reduce EV release in HeLa studies and other cancer models." (PMID 40722712, 2025). "The release of exosomal PD-L1 was inhibited in cancer cell lines when nSMase2 and Rab27a were experimentally knocked down." (PMID 38562933, 2024). "The exosome-mediated extracellular secretion of miRNAs occurs in many cancers, and RAB27A is a potent regulator of exosome secretion." (PMID 38685086, 2024). "Rab27A is a small GTPase-mediating exosome secretion, which participates in tumorigenesis of multiple cancer types." (PMID 38521810, 2024). "It has been reported that upregulation of Rab27a contributes to the progression and malignancy of cancer cells." (PMID 38715944, 2024). "Inhibition of Rab27a expression by RNAi can reduce the release of exosomes from cancer cells and inhibit the growth of tumors and the formation of metastatic clones." (PMID 37217932, 2023). "Reduction of exosome secretion via depletion of Rab27a in cancer cells or pharmacological inhibition of exosomal uptake at sites of future metastases was sufficient to impair PMN formation and decrease spontaneous metastasis in tumor bearing mice." (PMID 37217932, 2023).
cancer (continued). "Most importantly, amongst the four Rab GTPases analyzed, Rab27a protein levels is the one that correlates the best with the number of secreted vesicles by cancer cells in a linear regression analysis." (PMID 37641131, 2023). "Rab27a expression levels significantly increase in cancer cells treated with any of the two demethylating agents." (PMID 37641131, 2023). "In this study, it was found that knockdown of Rab27a reduced the protein levels of genes involved in exosomal biogenesis and secretion in cancer cells and promoted the proliferative activity of aspirin on NK cells." (PMID 37392173, 2023). "In order to identify the possible role of EVs in the cancer cells, we performed Rab27a knockdown in cells." (PMID 37005676, 2023). "To study the effect of cancer-derived EVs on cSCC growth, we inhibited EV-secretion by depletion of RAB27A, a protein controlling EV-secretion." (PMID 37495566, 2023). "In order to determine which is the best Rab GTPase to analyze as a surrogate marker for secretion of exosomes by cancer cells, we screened for four Rab GTPases (Rab5, Rab7, Rab27a and Rab27b) using three human PDAC cell lines (PANC-1, BxPC-3 and MIA PaCa-2)." (PMID 37641131, 2023). "Among the many Rab GTPases, Rab27a has been shown to regulate the late stages of the endocytic pathway mediating exosomes release from cancer cells, including in PDAC." (PMID 37641131, 2023). "Rab27a/b are aberrantly expressed in cancers, and they have a key function in cancer progression via their activity in exosome biogenesis." (PMID 36320056, 2022). "Rab27a is a GTPase known to play a pro-tumorigenic and pro-metastatic role in multiple cancer types through involvement in maturation, secretion and trafficking of exosomes, as well as MMP9." (PMID 35740692, 2022). "The value of Rab27a as a prognostic marker in cancer patients was assessed differentially by dataset (sample size), cancer type, and analysis program." (PMID 35053535, 2022). "In contrast to the observation that Rab27a expression was upregulated in clinical cancer patients, our analysis using public databases showed different correlations between mRNA and protein levels." (PMID 35053535, 2022). "Rab27A promotes the growth and invasion of multiple cancer types such as breast, lung and pancreatic, by enhancing secretion of chemokines, metalloproteases and exosomes." (PMID 35308027, 2022). "In fact, the release of sEV PD-1 was suppressed in a cancer cell model in which the RAB27A and nSMase2 genes, which are related to sEV secretion, were deleted, thereby increasing the response to ICBT through the activation of immune cells." (PMID 36077620, 2022). "RAB27a mRNA expression was shown to be increased in T4-stage cancer when compared to T1, T2, and T3 stages." (PMID 35205655, 2022). "In this case, the similarities and differences of Rab27a-mediated exocytosis between immune cells and in cancer should be established." (PMID 35053535, 2022). "Concerning the importance of Rab27A in the stemness status of cancer cells, there was a 2016 study that focused on the role played by miR-134-3p in human ovarian cancer stem cells." (PMID 34072080, 2021). "There are some studies on the expression of Rab27A in different cancer types and its prognostic relevance." (PMID 34072080, 2021). "Rab27a knockdown in invasive cancer cell lines decreased exosome secretion, and Rab27a-mediated exosomes increased cell migration, chemotaxis, and invasion." (PMID 34141705, 2021). "The exposure of cancer cells to hypoxia increased their exosome-medicated cisplatin efflux by upregulation of Rab27a." (PMID 34141705, 2021). "Since cancer cell lines overexpressed two subtypes of Rab proteins (Rab27a and Rab27b) involved in the process of exosome release, cancer cells are also considered as efficient exosome producers." (PMID 34503245, 2021). "The inhibition of Rab27a by APC therefore suggests an anti-cancer effect of APC by targeting Rab27a." (PMID 34444857, 2021).
cancer (continued). "Previous work has shown that Rab27a plays an important role in cell viability and proliferation in a range of cancers." (PMID 33282910, 2020). "Rab27a is a small Ras-like GTPase that has been shown to be differentially expressed in cancer and is known to contribute to EV biogenesis." (PMID 32355248, 2020). "All studies performed immunohistochemistry to evaluate Rab27A or Rab27B expression in the human cancer tissue, and the majority of the cut-off value were scoring system using staining intensity and proportion." (PMID 32839520, 2020). "Both Rab27A and Rab27B have been reported to promote the proliferation, enhance the invasion, and increase the chemo-resistance of cancer." (PMID 31438991, 2019). "Greater amounts of RAB5 and RAB27A proteins were expressed in cancer cells, compared to normal cells." (PMID 30918259, 2019). "Knockdown of Rab27A or Rab27B reduces exosome release in different cancer cell types, including bladder cancer cells, cervical cancer cells, breast cancer cells, melanoma cells, and lung adenocarcinoma cells." (PMID 31438991, 2019). "Both Rab27A and Rab27B have been reported to promote cell proliferation, enhance cell invasion, and increase chemoresistance of cancer." (PMID 30081925, 2018). "The majority of clinicopathological findings indicate that Rab27A and Rab27B have oncogenic roles in cancer." (PMID 30081925, 2018). "Altered expression of Rab27A/B is observed in various human cancers and contributes to cancer progression." (PMID 30081925, 2018). "The results showed that in Rab27A depleted 5637 cells, the number of invaded cancer cells was significantly decreased." (PMID 29088864, 2017). "Rab27A is a peculiar member in Rab family and has been suggested to play essential roles in the development of human cancers." (PMID 26070933, 2015). "The inhibition of RAB27A has been studied in cancer progression." (PMID 40722712, 2025). "Rab27a knockdown in cancer cells reduces EVs secretion, thereby inhibiting fatty liver formation." (PMID 40612230, 2025). "RAB27A protein expression in healthy donor MSCs was found to be relatively low in comparison to cancer cell lines, such as K562; however, in comparison to the healthy control, MSCs expression was considerably decreased in the MSCs samples of the two GS-2 patients (İK and YF)." (PMID 39474038, 2024). "Furthermore, the knockdown of Rab27A in an invasive cancer cell line reduced exosome secretion, whereas Rab27A-mediated exocytosis increased cell migration, chemotaxis, and invasion." (PMID 38203424, 2023). "Hence, our data shows that an epigenetic regulatory mechanism of Rab27a expression occurs specifically in cancer." (PMID 37641131, 2023). "Furthermore, the combinatorial treatment of VSV∆51-amiR-4 and GSK126 resulted in a significant decrease in cancer cell viability (P value = 0.0003), Rab27a-depletion in 4T1 cells abolished these effects (P value = 0.7193)." (PMID 35393414, 2022). "In addition, cancer cells can secrete a large number of exosomes, because the overexpressed Rab27a and Rab27b proteins in cancer cells are involved in the process of exosome release." (PMID 35701788, 2022). "The significant role of Rab27A in multiple cancer types and the minor role in adults suggest that Rab27A may be a suitable target to disrupt cancer metastasis." (PMID 35308027, 2022). "In our study, inhibiting LLC-EVs release by knocking down Rab27A expression could relieve fat loss and WAT browning in cancer cachectic mice." (PMID 33510128, 2021). "So the secretion of Rab27a and exosomes is intrinsically related to the invasion of cancer cells." (PMID 34141705, 2021). "Similarly, exosomes derived from Rab27a-overexpressing cancer cells elicited the efficient induction of antitumor immunity." (PMID 34141705, 2021).